HAUS3 (HAUS augmin like complex subunit 3)
Description:
Contributes to mitotic spindle assembly, maintenance of centrosome integrity and completion of cytokinesis as part of the HAUS augmin-like complex.
Synonyms: C4orf15; MGC4701; IT1; dgt3
Tractability: PROTAC: ubiquitination databases record sites on it; its protein half-life has been measured.
Gene: Protein-coding gene on chromosome 4 (2,227,464 to 2,242,133, reverse strand). Ensembl gene ENSG00000214367.
Subcellular location: Cytoplasm, cytoskeleton, microtubule organizing center, centrosome; Cytoplasm, cytoskeleton, spindle
Subcellular location (Human Protein Atlas): Microtubules; Primary cilium; Basal body; Cytokinetic bridge; Mitotic spindle
Pathways (Reactome):
Cell Cycle: AURKA Activation by TPX2; Loss of Nlp from mitotic centrosomes; Loss of proteins required for interphase microtubule organization from the centrosome; Recruitment of NuMA to mitotic centrosomes; Recruitment of mitotic centrosome proteins and complexes; Regulation of PLK1 Activity at G2/M Transition
Organelle biogenesis and maintenance: Anchoring of the basal body to the plasma membrane
Gene Ontology:
Molecular function: protein binding
Biological process: centrosome cycle; spindle assembly; microtubule organizing center organization; regulation of microtubule nucleation
Cellular component: centrosome; ciliary basal body; HAUS complex; microtubule cytoskeleton; mitotic spindle microtubule; cytosol; microtubule organizing center; mitotic spindle; spindle
Genetic constraint (gnomAD): Loss-of-function variants: 24 observed, 43.67 expected, observed/expected ratio (o/e) 0.55, 90% interval 0.4 to 0.77. The upper end of that interval is the gene's LOEUF score, 0.77, which puts it in group 3 of 6, group 1 being the genes least tolerant of losing a copy. Missense variants: 620 observed, 572.54 expected, observed/expected ratio (o/e) 1.08, 90% interval 1.01 to 1.16. Synonymous variants: 195 observed, 208.28 expected, observed/expected ratio (o/e) 0.94, 90% interval 0.83 to 1.05.
Homologues: Orthologues: chimpanzee HAUS3 (99% identical), rabbit HAUS3 (84% identical), guinea pig HAUS3 (82% identical), mouse Haus3 (74% identical), tropical clawed frog haus3 (46% identical), zebrafish haus3 (35% identical).
Diseases named in the same sentence as HAUS3 in open-access papers:
HAUS3 is named in the same sentence as 106 diseases in open-access papers, as found by Europe PMC text mining. Sharing a sentence is not in itself a finding about the gene and the disease. The quoted sentences say what the papers report.
breast carcinoma (40 papers, 2015 to 2026). "Augmin family genes have been less studied in cancer, and it has been found that HAUS3 is mutated in breast cancer and HAUS3 is a poor prognostic factor in liver cancer." (PMID 37161065, 2023). "This could be relevant as HAUS3 is sometimes mutated in breast cancer." (PMID 26269593, 2015).
glioma (21 papers, 2016 to 2023). A benign or malignant brain and spinal cord tumor that arises from glial cells (astrocytes, oligodendrocytes, ependymal cells). "Low expression of HAUS4 and HAUS6 and high expression of HAUS1, HAUS3, HAUS5, HAUS7, HAUS8 may be risk factors for poor prognosis in glioma patients." (PMID 37161065, 2023). "The research found that expression levels of the Augmin family genes HAUS1, HAUS3, HAUS4, HAUS5, HAUS6, HAUS7, and HAUS8 was all related with survival rates of glioma patients." (PMID 37161065, 2023).
lung cancer (18 papers, 2014 to 2025). A malignant neoplasm involving the lung. "For example, a 5hmC marker with elevated signals in lung cancer patients was distributed in the gene body region of HAUS3, a protein-coding gene that plays a key role in cytokinesis and mitosis." (PMID 35073982, 2022).
breast tumor (4 papers, 2013 to 2022). "In a study following a lobular human breast tumor, a mutation in HAUS3 was one of only five nonsynonymous coding mutations that were prevalent in the primary breast tumor and remained in the metastatic cancer nine years later." (PMID 26269593, 2015). "Of these variants a frameshift mutation, c.811delT, in HAUS3 was potentially interesting, because HAUS3 has been reported to be somatically mutated in a lobular breast tumour." (PMID 23383274, 2013).
tumor (96 papers, 2014 to 2025). "Among the neoantigens are well-known genes associated with tumor progression and metastases, such as HAUS3, NSDHL, MAGEA10, FNDC3B, TEAD1, DHX33, PGM5, and MLL2." (PMID 36607962, 2023).
cancer (80 papers, 2014 to 2026). A tumor composed of atypical neoplastic, often pleomorphic cells that invade other tissues. "Other interesting candidates previously related to cancer include CTNND1 and TPM2, for which alternative splicing events in both transcripts have been correlated with cancer, and HAUS3." (PMID 34496885, 2021). "HER2-enriched cancers involved four regulators of PLK1 activity at G2/M transition in the cell cycle, CEP63, CEP250, NEDD1, and HAUS3." (PMID 40700427, 2025).
HAUS3 also shares sentences with these, for which no sentence is quoted: melanoma (47 papers); bladder cancer (29); gastric cancer (26); hepatocellular carcinoma (24); colorectal cancer (23); ovarian carcinoma (18); cervical carcinoma (15); esophageal squamous cell carcinoma (14); lung adenocarcinoma (13); cholangiocarcinoma (12); lymph node metastasis (11); non-small cell lung carcinoma (11); osteosarcoma (10); head and neck squamous cell carcinoma (8); pancreatic cancer (8); colon cancer (7); schizophrenia (6); prostate carcinoma (5); esophageal cancer (4); infection (4); liver cancer (4); asthma (3); glioblastoma (3); small cell lung carcinoma (3); thyroid cancer (3); clear cell renal cell carcinoma (2); colon adenocarcinoma (2); diabetes (2); endometrial cancer (2); leukemia (2).
A further 70 diseases each share a sentence with HAUS3 in 2 papers or fewer.